PTH (parathyroid hormone)
Diseases named in the same sentence as PTH in open-access papers (continued):
Sharing a sentence is not in itself a finding about the gene and the disease.
vitamin D deficiency (continued). "Indeed, both had normal serum albumin-adjusted total calcium serum levels and high serum levels of PTH (106 and 102 pg/mmol, respectively (normal range: 15–65)) without vitamin D deficiency." (PMID 31979085, 2020). "Interestingly, although levels of serum Ca and IP did not decrease in the vitamin D-deficiency mouse group, levels of serum PTH tended to increase (not significant)." (PMID 32681041, 2020). "Our results do not support the hypothesis that elevated levels of PTH in combination with vitamin D deficiency are associated with fetal growth restriction." (PMID 33114615, 2020). "Given the interdependency of PTH and vitamin D, reference ranges for PTH may be overestimated if determined in a population of otherwise healthy individuals for whom vitamin D deficiency was not evaluated." (PMID 31273631, 2019). "The tumorigenic action of PTH excess may act without opposition because of vitamin D deficiency, which is frequently presented in patients with PHPT, and contribute to the increase of tumors formation like in patients in dialysis for terminal renal disease." (PMID 30581552, 2018). "The lack of expected changes in serum Ca, P, ALP, and PTH levels together with low concentrations of vitamin D deficiency and a normal serum Mg may result from the measurement method and/or from high DBP levels, and may not reflect a true vitamin D deficiency." (PMID 29357898, 2018). "It is not clear whether PTH levels might be also a surrogate marker for other functional consequences of vitamin D deficiency." (PMID 29271084, 2018). "We suggest that CKD G3a-G5 patients with progressively rising or persistently elevated PTH levels should be evaluated for modifiable factors, which now includes high phosphate intake and vitamin D deficiency; treatment decisions should not be based on a single elevated value." (PMID 30236082, 2018). "Vitamin D supplementation is used as a clinical treatment for hyperparathyroidism in addition to treating vitamin D deficiency caused by a multiple diseases and medications, although the dose of vitamin D required to suppress PTH in overweight-obese individuals is not yet determined." (PMID 28272298, 2017). "Thus, increased serum PTH concentrations due to vitamin D insufficiency might lead to low arterial compliance and high stiffness, resulting in increased CVD." (PMID 29088221, 2017). "Third, data on parathyroid hormone levels were not available as these could be elevated in states of vitamin D deficiency." (PMID 28192499, 2017). "The serum PTH threshold of 44 pg/mL, corresponding to the upper quartile of the PTH distribution in the young CHD patients, has been chosen to detect mild parathyroid function activation induced by vitamin D deficiency in young subjects with normal renal function." (PMID 26955207, 2016). "Similarly, we detected a negative correlation between vitamin D and PTH levels, and a negative correlation between alkaline phosphatase and vitamin D levels has been reported, emphasizing the effects of vitamin D deficiency in patients with FMF." (PMID 27121284, 2016). "Although vitamin D treatment may decrease PTH in persons taking TDF in the absence of measurable vitamin D deficiency, in our study TDF or IP exposure was a risk factor for not achieving PTH objective." (PMID 27699068, 2016). "Vitamin D insufficiency may be defined as the level below which PTH begins to rise." (PMID 26000306, 2015). "Notably, hyperparathyroidism was found in 34.2% (13/38) of subjects with severe vitamin D deficiency, while no subjects with vitamin D sufficiency had elevated PTH." (PMID 24902694, 2014). "In addition, vitamin D insufficiency also induced elevations in PTH, which could adversely affect glucose metabolism." (PMID 25350669, 2014). "Although the explanation for this finding is unclear, the adolescent vitamin D deficiency detected may be a more acute finding as opposed to long standing vitamin D deficiency in adults with chronic PTH elevation." (PMID 23724340, 2013).
vitamin D deficiency (continued). "In addition, high serum parathyroid hormone has been identified as a risk factor for falls independent of vitamin D deficiency." (PMID 22980233, 2012). "In this study, we show that prolonged treatment of postmenopausal women with pHPT and coexisting vitamin D deficiency for up to 54 months with various vitamin D preparations significantly reduced serum PTH concentrations, with no adverse effects on serum adjCa levels and renal function tests." (PMID 23781299, 2012). "Recent studies indicate that treatment of vitamin D deficiency may have the potential to reduce circulating PTH levels in patients with pHPT, without adverse effects on serum-adjusted calcium (adjCa) levels." (PMID 23781299, 2012). "Bone metabolism study was suggestive of high parathyroid hormone (PTH) (308 pg/mL), ALP (3781 IU/L), vitamin D insufficiency (17 ng/mL), phosphate (3.46 mg/dL), and normal calcium (8.6 mg/dL)." (PMID 40625472, 2025). "Of note, a component of secondary hyperparathyroidsim cannot be entirely ruled out (and it might be, in fact, overlapped), but there was only a small degree of renal dysfunction and the complete correction of vitamin D deficiency did not explain the persistent high PTH values." (PMID 40981138, 2025). "Four cases of operative failure were observed, all attributable to factors beyond intraoperative PTH criteria, including parathyroid carcinoma with metastatic disease, previous extensive neck surgery, non-localizing or anatomically challenging adenomas, and vitamin D deficiency." (PMID 41393630, 2025). "Here, we have explored an alternative viewpoint by investigating whether vitamin D deficiency can exert downstream effects on parathyroid tissue, testing the hypothesis that low vitamin D status could act as a potential driver of PHPT development and PTH hypersecretion." (PMID 36992820, 2023). "Although vitamin D insufficiency is more prevalent among African Americans because their pigmentation reduces vitamin D production in the skin, they have lower rates of osteoporotic fractures, which may be explained by bone-protective adaptations and skeletal resistance to the parathyroid hormone." (PMID 35340470, 2022). "Treatment for patients with intermediate-stage non-dialysis CKD and vitamin D deficiency should aim to replenish 25(OH)D levels with a nutritional form of vitamin D. If secondary hyperparathyroidism is present, treatment should aim to control parathyroid hormone levels early in the disease course." (PMID 34626363, 2022). "Furthermore, there were no intact PTH levels available, which might have been useful when assessing the effect of vitamin D deficiency on mortality." (PMID 36338833, 2022). "However, not all vitamin D deficiency patients have increased PTH levels." (PMID 34580590, 2021). "Furthermore, the 25(OH)D concentration, where the PTH concentration begins to increase or no longer decreases, may mark vitamin D deficiency." (PMID 33109180, 2020). "Commonly, increased serum parathyroid hormone (PTH) levels and vitamin D insufficiency are universal among CAPD patients and are mostly attributed to chronic kidney disease-mineral and bone disorder (CKD-MBD)." (PMID 32423377, 2020). "Vitamin D insufficiency is pragmatically defined as the level of 25(OH)D below which PTH increases, and SHPT has been suggested as the best marker of vitamin D insufficiency." (PMID 32375334, 2020). "Parathyroid hormone (PTH) concentrations are routinely measured in the diagnosis and management of bone and kidney diseases, but reference ranges can be overestimated if determined in otherwise healthy individuals for whom vitamin D deficiency was not evaluated." (PMID 31273631, 2019). "Vitamin D and calcium have been investigated with regards to hypertensive disorders of pregnancy and functional vitamin D deficiency (low 25(OH)D plus elevated PTH), rather than low 25(OH)D alone, may adversely affect gestational blood pressure and preeclampsia." (PMID 30018262, 2018).
vitamin D deficiency (continued). "However, the PTH and calcium could not change the association between vitamin D deficiency and functional outcome events." (PMID 29437901, 2018). "In addition, this patient with chronic kidney disease had 25-OH vitamin D insufficiency (56 nmol/L), for which she was prescribed oral cholecalciferol (100,000 IU per month) in spite of normal serum calcium (2.21 mmol/L) and parathyroid hormone (PTH) levels (38 ng/L)." (PMID 30290590, 2018). "However, the skeletal abnormalities could not be simply explained by the known causes of a vitamin D deficiency or an increased PTH concentration." (PMID 28690912, 2017). "Therefore, serum concentration of PTH may not be used clinically as an indicator of vitamin D deficiency and regardless of calcium and PTH results, serum 25(OH)D should be measured if vitamin D deficiency or insufficiency is predicted." (PMID 28473985, 2017). "Furthermore, eGFR did not predict hip fracture, vitamin D deficiency or elevated PTH." (PMID 26910625, 2016). "First, in our study no measurements of serum levels of parathyroid hormone and Vitamin D are available for most of the population, so it is impossible to absolutely exclude confounding factors such as primary hyperparathyroidism and secondary hyperparathyroidism due to vitamin D deficiency." (PMID 25924883, 2015). "The concept of NPHPT was first described in detail in 2003, and although it has evolved from the notion of resistance to PTH to the subclinical form of HPTH, its connection with vitamin D deficiency is not clarified even after 20 years." (PMID 39040613, 2024). "There is a clinical need to define a threshold 25(OH)D concentration below which serum PTH is no longer suppressed and considered an endocrine indicator of physiological vitamin D insufficiency." (PMID 36721726, 2023). "While many studies have suggested that PTH levels start to increase at 25(OH)D levels below 70 nmol/L, individual patients with vitamin D insufficiency do not always have high PTH levels." (PMID 36936151, 2023). "As expected, our VDD and HFDV groups presented elevated PTH levels in relation to SD and HFD groups, demonstrating the negative feedback caused by vitamin D deficiency." (PMID 36466412, 2022). "Our study showed that age over 40 years is associated with a 5.5 pg/mL increase in serum PTH level independent of GFR and vitamin D compared to 18-39 years of age group in subjects without CKD or vitamin D deficiency." (PMID 33995282, 2021). "Interestingly, although median PTH was significantly higher in subjects with vitamin D deficiency compared with subjects with 25(OH)D above 12 ng/mL, the correlation between PTH and 25(OH)D was not significant anymore in subjects with vitamin D deficiency and impaired renal function." (PMID 33995282, 2021). "Multiple regression models showed that serum PTH was negatively correlated with both 25(OH)D and GFR in adult subjects without vitamin D deficiency (serum 25(OH)D≥12 ng/mL)." (PMID 33995282, 2021). "After adjusting for serum 25(OH)D and GFR, age over 40 years was significantly associated with a 5.5 pg/mL increase in serum PTH in adult subjects with normal renal function (GFR≥60 mL/min/1.73m2) and no vitamin D deficiency (25(OH)D≥12 ng/mL)." (PMID 33995282, 2021). "In contrast, 1,25(OH)2D has a short half-life of ca. 15 h and its serum concentration—closely regulated by PTH, FGF23, calcium and phosphate—does not appreciably decrease in the case of vitamin D deficiency." (PMID 33066259, 2020). "Therefore, the preoperative PTH level in vitamin D deficiency may not reflect the reality." (PMID 32555278, 2020). "The findings of our study suggest that even if serum vitamin D levels in a mother-neonate pair are lower than 10 ng/ml, this finding is not sufficient to diagnose vitamin D deficiency, regardless of serum Ca, P, Mg, ALP and PTH levels." (PMID 29357898, 2018).
vitamin D deficiency (continued). "In those studies, the prevalence of vitamin D deficiency is only based on serum vitamin D levels measured with immunoassays, regardless of serum Ca, P, Mg, ALP and PTH levels." (PMID 29357898, 2018). "As in the patients with vitamin D deficiency, PI based therapies and those with TDF exposure were associated with a higher risk of not achieving PTH levels under 65 pg/mL." (PMID 27699068, 2016). "Though we could not evaluate the mechanism of poorer pulmonary function in PTH elevation, PTH might be a more effective biomarker than vitamin D for COPD patients, especially in regions with a high prevalence of vitamin D insufficiency." (PMID 26398210, 2015). "PTH may be a better biomarker for COPD patients, especially in regions with a high prevalence of vitamin D insufficiency." (PMID 26398210, 2015). "Another important issue is the treatment approach in subjects with vitamin D deficiency whose ALP and PTH levels are not elevated." (PMID 21318069, 2008). "Among the newborns with severe vitamin D deficiency (<12.5 ng/ml), serum ALP was higher (331.4 ± 95 compared with 606.9 ± 270.3, p = 0.001), while there was not a significant different in PTH or calcium in cord blood." (PMID 17295904, 2007). "It is characterized by elevated parathyroid hormone (PTH) levels with normal albumin-corrected calcium, in the absence of secondary causes of hyperparathyroidism, such as vitamin D deficiency, medications influencing calcium metabolism, and chronic kidney disease." (PMID 40981138, 2025). "Subclinical vitamin D insufficiency should also not be overlooked because of a normal PTH level." (PMID 34202743, 2021). "The risk of lower serum PTH values due to active vitamin D treatment is higher in subjects with impaired renal function and might explain the lack of association between 25(OH)D and PTH in subjects with CKD and vitamin D deficiency." (PMID 33995282, 2021). "In those with vitamin D deficiency and CKD, age was not a significant predictor of PTH anymore." (PMID 33995282, 2021). "Thus, the proposed defining of vitamin D insufficiency as a serum vitamin D < than 30 ng/ml (75 nmol/liter), based on serum PTH suppression, is not supported by the literature review." (PMID 31341474, 2019). "Even if maternal and neonatal serum vitamin D concentrations are consistent with each other in terms of low serum vitamin D levels (< 10 ng/ml), this finding alone is not sufficient to diagnose vitamin D deficiency, without taking into consideration the serum Ca, P, Mg, ALP, and PTH levels." (PMID 29357898, 2018). "The major limitations of our study include dietary intake, biochemical variables (calcium, parathyroid hormone), HIV status and latent TB infections, all of which could affect vitamin D deficiency, were not considered in this study." (PMID 28490367, 2017). "Concerning PTH data, we found significant higher levels (pg/mL) of the respective hormone in VDD (1,250±155) and VDD+IRI (2,187±336), showing the negative feedback caused by vitamin D deficiency in these groups." (PMID 25222475, 2014). "Parathyroid cells that have VDR and vitamin D deficiency, with or without low expression of VDR in these cells, causes an increase in circulating levels of the parathyroid hormone (PTH), which is responsible for a number of metabolic alterations in skeletal and non-skeletal tissues." (PMID 24747593, 2014).
secondary hyperparathyroidism (680 papers, 2006 to 2026). Overproduction of parathyroid hormone in response to influence external to the parathyroid glands. "PTH is elevated in serum 25(OH)D deficiency (secondary hyperparathyroidism), which can reduce muscle strength." (PMID 40083058, 2025). "The loss was associated with low levels of vitamin D, secondary hyperparathyroidism (elevated PTH), and increased bone turnover." (PMID 40867540, 2025). "Phosphate dosing was limited by rising parathyroid hormone levels – reflecting the risk of secondary hyperparathyroidism – and serum phosphorus levels remained well below the lower limit of normal (1.4 mg/dL in both twins, reference range: 2.7–4.5 mg/dL)." (PMID 40980824, 2025). "In cases of 25-OH-D3 deficiency, serum PTH levels increase, leading to secondary hyperparathyroidism." (PMID 40075885, 2025). "The relationship between UA and PTH has been recognized for many years, and substantial evidence supports this association in primary hyperparathyroidism, secondary hyperparathyroidism, and even in the general population." (PMID 40710544, 2025). "Elevated levels of PTH (as observed in primary and secondary hyperparathyroidism) have been linked to an increased occurrence of heart failure, hypertension, cardiac arrhythmias, left ventricular hypertrophy, and valvular calcific disease." (PMID 39860501, 2025). "Research investigating PTH in schizophrenia has shown that with low vitamin D and high PTH levels, this population is at risk of developing secondary hyperparathyroidism." (PMID 40867540, 2025). "Hypomagnesemia can lead to impaired PTH secretion and action, secondary hyperparathyroidism, BMD loss, increased osteoporosis risk, and potential cardiovascular complications." (PMID 41295288, 2025). "One component of CKD-MBD is high circulating parathyroid hormone (PTH) leading to secondary hyperparathyroidism which is postulated to cause high bone turnover with resorption exceeding formation favoring bone loss." (PMID 40408439, 2025). "ImP also correlated positively with PTH, a marker of secondary hyperparathyroidism commonly seen in advanced CKD and associated with mineral–bone homeostasis, cardiovascular risk, and mortality." (PMID 41362635, 2025). "Subclinical hyperparathyroidism is characterized by elevated PTH levels ≥ 45 ng/mL and normal blood calcium levels in three consecutive measurements over a 3–6 month period after exclusion of causes of secondary hyperparathyroidism." (PMID 40709988, 2025). "As kidney disease advances to its end stage, a deficiency in calcium and 1,25(OH)2D3 coupled with elevated phosphate levels instigates the onset of secondary hyperparathyroidism, causing a compensatory elevation in parathyroid hormone (PTH)." (PMID 40725208, 2025). "Secondary hyperparathyroidism is the most common cause of elevated PTH in patients with chronic kidney disease (CKD)." (PMID 41210046, 2025). "Secondary hyperparathyroidism (SHPT) is a hallmark complication of end-stage renal disease (ESRD) characterized by excessive parathyroid hormone (PTH) secretion and parathyroid gland hyperplasia." (PMID 40725638, 2025). "It is a condition characterized by elevated PTH > 45 ng/mL, normal blood calcium levels in three consecutive measurements over a 3–6 month period, and exclusion of other causes of secondary hyperparathyroidism." (PMID 40709988, 2025). "Low vitamin D status can lead to lower Ca absorption and secondary hyperparathyroidism, i.e. to increased parathyroid hormone (PTH) concentrations, and further to bone loss." (PMID 40936036, 2025). "Secondary hyperparathyroidism is caused by a variety of conditions that lead to hypocalcemia, prompting the parathyroid glands to adjust by secreting an excessive amount of PTH." (PMID 39403580, 2024). "The connection between elevated creatinine, urea, and increased PTH levels is linked with secondary hyperparathyroidism." (PMID 39484207, 2024).